RN7SL574P (RNA, 7SL, cytoplasmic 574, pseudogene)
Gene: Miscellaneous RNA gene on chromosome 1 (3,782,815 to 3,783,111, forward strand). Ensembl gene ENSG00000266075.
Homologues: Orthologues: chimpanzee Metazoa_SRP (94% identical), macaque Metazoa_SRP (94% identical). Paralogues in human: RN7SL1 (81% identical), RN7SL2 (80% identical), RN7SL3 (79% identical), RN7SL665P (78% identical), RN7SL147P (77% identical), RN7SL220P (77% identical), RN7SL655P (77% identical), RN7SL127P (77% identical), RN7SL278P (77% identical), RN7SL296P (77% identical), RN7SL321P (77% identical), RN7SL566P (77% identical), and 704 more.